PPARA (peroxisome proliferator activated receptor alpha)
Diseases named in the same sentence as PPARA in open-access papers (continued):
Sharing a sentence is not in itself a finding about the gene and the disease.
energy metabolism disorders (3 papers, 2022 to 2025). "This study, utilizing 18F-FDG MicroPET/CT dynamic imaging combined with molecular biology techniques, systematically reveals, for the first time, the dual mechanism by which the SGLT2 inhibitor EMPG improves energy metabolism disorders in HF by regulating the PPARα signaling pathway." (PMID 41181599, 2025).
Erythema (3 papers, 2019 to 2023). Redness of the skin, caused by hyperemia of the capillaries in the lower layers of the skin. "Interestingly, PPARA mRNA levels were reduced in KCs after UVB irradiation and topical application of a cream containing 5% WY14,643, a well-known PPARα agonist, alleviated UVB-induced erythema." (PMID 31470652, 2019).
esophageal cancer (3 papers, 2010 to 2023). A primary or metastatic malignant neoplasm involving the esophagus. "PPARγ suppresses the growth and invasion of human colon and gastric and esophageal carcinoma cells, and both PPARγ and PPARα have anti-inflammatory actions." (PMID 21318167, 2010).
Hyperbilirubinemia (3 papers, 2014 to 2023). An increased amount of bilirubin in the blood. "As for HO-1, the PPARα-dependent induction of UGT1A1 expression is pharmacologically relevant for the treatment of hyperbilirubinemia." (PMID 25147562, 2014). "Transgenic mice that are homozygous for the human UGT1A1*28 (HuUGT*28) exhibit moderate hyperbilirubinemia and are protected against the development of dietary-induced hepatic steatosis via decreased serine 73 phosphorylation, an inhibitory site of the PPARα protein." (PMID 36830621, 2023). "Similar to our other findings with mild hyperbilirubinemia, GNUR-treated obese mice had activated PPARα pathways that reduced hepatic lipid content and increased liver glycogen." (PMID 36830621, 2023).
intestinal cancer (3 papers, 2012 to 2019). "Our results demonstrate that inhibition of Wnt/β-catenin signaling increased, while activation of Wnt/β-catenin pathway decreased, the expression and transcriptional activity of PPARγ, but not PPARα, in intestinal cancer cell lines." (PMID 31546785, 2019).
intrahepatic cholestasis (3 papers, 2013 to 2025). A cholestasis characterized by impairment of the bile flow caused by obstruction located in the liver. "Taken together, these data provide compelling evidence that PPARα is a potential target of DCHT in the treatment of intrahepatic cholestasis with liver injury." (PMID 35370715, 2022). "PPARα agonist fenofibrate was able to mimic the cytoprotective effect of DCHT on intrahepatic cholestasis, which was abolished by the PPARα antagonist GW6471." (PMID 35370715, 2022). "Taken together, the present study provides compelling evidence that DCHT is a promising formula against acute intrahepatic cholestasis with hepatotoxicity which works via PPARα activation." (PMID 35370715, 2022). "Previous animal studies have demonstrated that DCHD targets the PPARα signaling pathway governing bile acid metabolism, effectively alleviating liver injury induced by both α-naphthylisothiocyanate-triggered intrahepatic cholestasis and bile duct ligation-induced extrahepatic cholestasis." (PMID 41378216, 2025). "KEGG enrichment and western blot analyses showed that signaling axes of JNK/IL-6/NF-κB/STAT3 related to PPARα might be the principal pathway DCHT affects intrahepatic cholestasis." (PMID 35370715, 2022). "Fibrates might be effective in prevention of intrahepatic cholestasis produced by estrogens and CPZ, and this effect was mainly due to PPARα agonist mechanism; however, other mechanisms might play part in bezafibrate and gemfibrozil actions." (PMID 23997763, 2013). "Our article is the first one studying the effect of three different fibrates on EE & CPZ induced intrahepatic cholestasis and focusing on the mechanism of their effect and whether it is PPARα dependent or not." (PMID 23997763, 2013). "A combination of PPARα agonist fenofibrate and UDCA could decrease serum AST, ALT, ALP, γ-glutamyl transpeptidase, and TG in PBC (classic intrahepatic cholestasis) patients, who are not responsive to UDCA alone." (PMID 35370715, 2022).
Kidney Cyst (3 papers, 2017 to 2024). Abnormal fluid filled sac within the kidney, either acquired or congenital. "Kidney cysts in mouse and human ADPKD have increased renal expressions of miR-17, which represses oxidative phosphorylation and FAO by inhibiting peroxisome proliferator-activated receptor alpha (PPARα), a regulator of lipid metabolism." (PMID 37241147, 2023).
Leydig cell tumor (3 papers, 2020 to 2022). A sex cord-stromal tumor occurring in the testis and rarely in the ovary. "It is worth noting that that a long-term exposure to PPARα-mediated herbicide (2,4-Dichlorophenoxy acetic acid) causes disruption of cholesterol/testosterone homeostasis in mouse Leydig cells and results in the development of Leydig cell tumors." (PMID 35740412, 2022). "In fact, in Leydig cell tumors, greater expression of GPER and a reduction of the PPARα, β and γ expression are correlated with the alterations in several lipid- and cholesterol-associated proteins, determining disturbances that could be related to tumorigenesis and cancer progression." (PMID 32957524, 2020).
lipidosis (3 papers, 2017 to 2022). "Alterations in PPARα target gene expression may be causative to a decrease in fatty acid oxidation but an increase in fatty acid uptake, which subsequently accounts for the severe hepatic lipidosis observed in mice and cell culture experiments." (PMID 34867397, 2021).
myocarditis (3 papers, 2016 to 2025). Myocarditis is a condition that is characterized by inflammation of the heart muscle (myocardium). "This balance between reducing harmful Th17 activity and promoting Treg function makes PPARα an effective target for treating both autoimmune and ICI-related myocarditis." (PMID 40356915, 2025). "By reprogramming immune status through the PPARα pathway, myocardial inflammation and fibrosis can be mitigated, addressing the severe cardiac complications seen in ICI-induced myocarditis." (PMID 40356915, 2025).
pancreatitis (3 papers, 2017 to 2025). Inflammation of the pancreas. "In conclusion, the inhibition of PPARα signaling pathway and the fatty acid degradation pathway may lead to the further disorder of lipid metabolism, which can aggravate pancreatitis." (PMID 28389636, 2017). "Our study also provided the first evidence that the disorders of PPARα signaling pathway and fatty acids degradation pathway are involved in the course of APFL, which sheds some new insight on our understanding of the pathophysiology of pancreatitis." (PMID 28389636, 2017).
paraganglioma (3 papers, 2017 to 2022). A benign or malignant neoplasm arising from paraganglia located along the sympathetic or parasympathetic nerves. "These compounds were able to antagonize PPARα at low micromolar concentrations, and displayed also interesting antiproliferative effects when tested in paraganglioma, glioblastoma, colorectal and pancreatic cancer cell models." (PMID 36015085, 2022). "Interestingly, the benzothiazole derivative 2b showed a marked cytotoxic effect, mainly in paraganglioma cells, with a dose-dependent inhibition profile and a potency comparable to that of the commercially available PPARα antagonist GW6471." (PMID 36015085, 2022).
pituitary tumor (3 papers, 2009 to 2024). A benign or malignant neoplasm affecting the pituitary gland. "As already mentioned, the prolactin gene is activated by PPARα as demonstrated in a rat pituitary tumor cell line and in reporter gene assays." (PMID 20011657, 2009). "Indeed, several AIP binding partners, including PPARα and NME1 (a tumor suppressor that negatively regulates cell migration, motility, and proliferation and has a negative correlation with pituitary tumor extension into the cavernous sinus) have been associated with pituitary tumorigenesis." (PMID 38479600, 2024). "Additionally, PPARα, PGC-1α, and FOXO1 ligands linked to acetylcarnitine may participate in the signaling pathways of prolactinoma, while SREBP-1c, LXRα/β, PPARγ, HIF-1α, PPARα, PGC-1α, and FOXO1 are likely involved in the signaling of nonfunctional pituitary tumors." (PMID 39669498, 2024).
pyometra (3 papers, 2023 to 2025). "The expression of related lipid synthesis proteins such as ACC1, FASN, SREBP-1c, and PLIN2 was upregulated, while PPARα and PGC1α were downregulated in bitches with pyometra." (PMID 40082867, 2025). "The uterine tissue samples of dogs with pyometra exhibits severe inflammatory infiltration, which can potentially result in the downregulation of PPARα and its co-activator PGC-1α." (PMID 40082867, 2025). "This study demonstrates that dysregulated lipid metabolism is a critical driver of canine pyometra progression, characterized by coordinated upregulation of ACC1, FASN, SREBP-1c, PLIN2 and suppression of PPARα and PGC1α." (PMID 40082867, 2025). "Given the crucial roles that PPARα and PGC1α play in oxidative stress, lipid metabolism, and inflammation, gaining a deeper understanding of the specific regulatory mechanisms governing PPARα and PGC-1α in pyometra will be pivotal for unraveling the nature of uterine pathology." (PMID 40082867, 2025).
renal dysfunction (3 papers, 2019 to 2023). "In patients with CKD, the expressions of PPARα target genes related to FAM in PTECs are decreased, with deficiencies in renal FAM associated with the progression of renal dysfunction." (PMID 34207854, 2021). "However, because most PPARα agonists are excreted primarily through the kidneys, patients with renal dysfunction may experience cumulative renal toxicity requiring dose adjustment, which is a limitation of this treatment regimen." (PMID 31698825, 2019).
retinal degeneration (3 papers, 2017 to 2023). Degeneration of the retina. "We next characterized retinal mitochondrial activity in Pparα-/- mice after the onset of retinal degeneration." (PMID 29183319, 2017). "Taken together, these findings suggest that endogenous PPARα is essential for retinal neuronal survival under normal conditions, and that PPARα activation protects against retinal degeneration in an AMD-like model with photoreceptor energy deficits." (PMID 29183319, 2017). "We found that endogenous PPARα is essential for the maintenance and survival of retinal neurons, with Pparα-/- mice developing retinal degeneration first detected at 8 weeks of age." (PMID 29183319, 2017). "Indeed, we have previously reported that the PPARα agonist fenofibrate protected the retina against ERG decline and retinal degeneration in diabetic mice." (PMID 36497130, 2022).
sarcoidosis (3 papers, 2015 to 2022). Sarcoidosis is a multisystemic disorder of unknown cause characterized by the formation of immune granulomas in involved organs. "Here we noticed a significantly lower PPARα mRNA expression in sarcoidosis patients compared with HC." (PMID 25969669, 2015). "In BAL CD4+ T cells, we noticed a significantly lower PPARα mRNA expression in sarcoidosis patients compared with HC." (PMID 25969669, 2015). "Thus, PPARα or PPARγ could be potential therapeutic targets in sarcoidosis." (PMID 25969669, 2015). "Our results suggest that the reduced expression of PPARα and PPARγ contribute to the persistent T-cell driven immunoresponse noted in non-resolving sarcoidosis, common in non-LS patients." (PMID 25969669, 2015). "Since fibrate drugs such as gemfibrozil are ligands for PPARα, the reduced expression of PPARα in T cells of sarcoidosis patients without LS may suggest that this class of drugs may also become candidate for treatment of sarcoidosis." (PMID 25969669, 2015). "The lower protein expression of PPARα and PPARγ could contribute to the persistent T-cell driven inflammation noted especially in non-resolving sarcoidosis, common in non-LS patients." (PMID 25969669, 2015).
skin aging (3 papers, 2013 to 2022). The gradual irreversible changes in structure of skin that occur as a result of the passage of time.. "PPARα has been shown to play important roles in age-related inflammatory diseases and skin aging." (PMID 27611371, 2016).
squamous cell carcinoma (3 papers, 2016 to 2022). A carcinoma arising from squamous epithelial cells. "A mutual influence among PPAR isoforms has been observed in human squamous carcinoma cells SCC-15, where silencing PPARγ caused an increase of PPARα and β mRNA." (PMID 34829605, 2021).
vitamin D deficiency (3 papers, 2020 to 2025). A nutritional condition produced by a deficiency of VITAMIN D in the diet, insufficient production of vitamin D in the skin, inadequate absorption of vitamin D from the diet, or abnormal conversion of vitamin D to its bioactive metabolites. "Prolonged vitamin D deficiency reduces muscle health by decreasing mtDNA content and the expression of critical biogenesis-related factors (for example, PGC-1α, NRF1, NRF2, PPARα, and COXIV)." (PMID 38004107, 2023).
α-synucleinopathy (3 papers, 2021 to 2025). "Our data also indicate that in addition to PPARα, RXR overexpression in mice with experimental α-synucleinopathy enhances NURR1 production in SNpc." (PMID 40422188, 2025).
acute pancreatitis (2 papers, 2021 to 2026). An acute inflammatory process that leads to necrosis of the pancreatic parenchyma. "In this study, we identified NorCA's role as a novel immunomodulator that alleviates acute pancreatitis through peroxisome proliferator-activated receptor α (PPARα)-mediated macrophage reprogramming and efferocytosis." (PMID 42196402, 2026).
airway hyperresponsiveness (2 papers, 2007 to 2011). "PPARα deficient mice showed increased eosinophilia, airway hyperresponsiveness, increased IL-6, IL-13 and eotaxin production in lung extracts as well as enhanced serum concentration of antigen-specific IgE." (PMID 21382489, 2011). "In murine models of allergen-induced inflammation, PPARα and PPARγ ligands reduce the influx of inflammatory cells, cytokine and mucus production, collagen deposition, and airways hyperresponsiveness." (PMID 18000530, 2007).
allergic rhinitis (2 papers, 2005 to 2022). Inflammation of the nasal mucous membranes caused by an IgE-mediated response to external allergens. "Neither PPARα nor βδ exhibited any difference in their expression when specimens from healthy volunteers were compared with samples obtained from patients with symptomatic allergic rhinitis." (PMID 16271155, 2005).
ampullary cancer (2 papers, 2021 to 2023). "Further a GSEA of the KEGG, Hallmark, Reactome, and Gene Ontology databases revealed that PPARA and lipid metabolism-related genes were enriched in our specimens of ampullary cancer and in the NCBI GSE39409 database." (PMID 33390794, 2021). "According to our results, upregulation of PPARA and lipid metabolism-related genes are potential pathways in the carcinogenesis and development of ampullary cancer." (PMID 33390794, 2021). "Expressions of PPARA messenger (m)RNA and the PPAR-α protein were higher in clinical samples and cell lines of ampullary cancer." (PMID 33390794, 2021). "PPARA and lipid metabolism-related genes can serve as important biomarkers in ampullary cancer patients." (PMID 33390794, 2021). "Our results identified PPARA and lipid metabolism-related genes as being upregulated in ampullary cancer." (PMID 33390794, 2021). "We also found PPARA expression in cell lines and clinical samples from ampullary cancer." (PMID 33390794, 2021). "Expression of PPARA mRNA in ampullary cancer cell lines was higher than in other cancer cell lines." (PMID 33390794, 2021). "Expressions of PPARA mRNA and PPAR-α protein were also detected in clinical samples and cell lines of ampullary cancer." (PMID 33390794, 2021). "From the MetaCore analysis, genes of peroxisome proliferator-activated receptor alpha (PPARA) and retinoid X receptor (RXR)-regulated lipid metabolism were overexpressed in ampullary cancer tissues." (PMID 33390794, 2021).
angiosarcoma (2 papers, 2019 to 2021). A malignant tumor arising from the endothelial cells of the blood vessels. "In conclusion, we report potent inhibitory effects of the cholesterol-lowering drug fenofibrate in MS1 VEGF angiosarcoma cells, which were independent of PPARα and NFκB." (PMID 31004117, 2019). "Data from the current study illustrate that fenofibrate exerted potent anti-proliferative actions in MS1 VEGF angiosarcoma cells, which were independent of PPARα and NFκB." (PMID 31004117, 2019).
Asthenozoospermia (2 papers, 2023 to 2026). "Palmitic acid may rescue the damaged spermatogenesis process of asthenozoospermia-model mice via enhancing PPARA expression." (PMID 37484950, 2023).
autosomal dominant polycystic kidney disease (2 papers, 2020 to 2022). Autosomal dominant form of polycystic kidney disease. "PPARα was shown to be downregulated in aggressive mouse models of autosomal dominant polycystic kidney disease (ADPKD) and primary human ADPKD cells, suggesting that decreased PPARα function may underlie the impaired FAO and oxidative phosphorylation in ADPKD." (PMID 35308207, 2022).
B cell lymphoma (2 papers, 2014 to 2022). "The PPARα agonist fenofibrate has further been demonstrated to suppress B cell lymphoma in mice through the modulation of lipid metabolism." (PMID 35954274, 2022). "B cell lymphoma cells express extremely low levels of PPARα; therefore, fenofibrate did not increase lipid utilization in the tumors but enhanced the clearance of lipids and blocked hepatic lipid release, leading to reduced tumor growth." (PMID 35954274, 2022).
cerebral infarct (2 papers, 2023 to 2025). "Medioresinol, a PGC-1α activator, reduces cerebral infarct volume and blood‒brain barrier permeability through the PPARα/GOT1 axis, inhibits endothelial cell pyroptosis, and promotes long-term neurobehavioral recovery." (PMID 38102696, 2023).
chronic kidney failure (2 papers, 2024). "Fibrates, the most commonly used PPARα agonists, are mainly excreted by the kidneys, thus limiting their use in patients with chronic kidney failure due to potential kidney-related complications." (PMID 38256023, 2024). "Mouse models further corroborated the link between low PPARα expression and the progression of fibrosis, suggesting that PPARα agonists hold potential as therapeutic drugs for chronic kidney failure." (PMID 38256023, 2024). "Patients with chronic kidney failure exhibited reduced expression of renal PPARα." (PMID 38256023, 2024).
diabetic eye disease (2 papers, 2022 to 2024). A group of disorders affecting the eye in patients with diabetes mellitus. "This is consistent with the findings noted in human liver and diabetic eye disease mice, indicating that PPARα is a target gene of miR-21." (PMID 35222033, 2022).
eosinophilia (2 papers, 2007 to 2018). "In PPARα-deficient Balb/c mice sensitized and challenged with OVA, there were greater increases in lung inflammation, airway eosinophilia, and antigen-specific serum IgE levels than in wild-type OVA-treated mice." (PMID 18000530, 2007).
follicular lymphoma (2 papers, 2025 to 2026). Follicular lymphoma is a form of non-Hodgkin lymphoma characterized by a proliferation of B cells whose nodular structure of follicular architecture is preserved. "Here, we found that PPARα is frequently low-expressed in transformed follicular lymphoma, and therapeutic activation of PPARα significantly represses the progression of t-FL in cell line-derived xenograft (CDX) and primary t-FL patient-derived xenograft (PDX) models in vivo." (PMID 40959276, 2025).
gastric tumors (2 papers, 2017 to 2025). "Analysis of public transcriptomic datasets revealed that peroxisome proliferator-activated receptor α (PPARα) is significantly downregulated in EBVaGC compared with EBV-negative gastric tumors." (PMID 40732023, 2025).